SLC25A23 (solute carrier family 25 member 23)
Description:
Electroneutral antiporter that mediates the transport of adenine nucleotides through the inner mitochondrial membrane. Originally identified as an ATP-magnesium/inorganic phosphate antiporter, it also acts as a broad specificity adenyl nucleotide antiporter. By regulating the mitochondrial matrix adenine nucleotide pool could adapt to changing cellular energetic demands and indirectly regulate adenine nucleotide-dependent metabolic pathways. Also acts as a regulator of mitochondrial calcium uptake and can probably transport trace amounts of other divalent metal cations in complex with ATP. In vitro, a low activity is also observed with guanyl and pyrimidine nucleotides.
Synonyms: SCaMC-3; APC2; MCSC2; SCAMC3; FLJ30339; MGC2615
Tractability: Antibody: UniProt predicts a signal peptide or a membrane-spanning region. PROTAC: ubiquitination databases record sites on it; its protein half-life has been measured.
Gene: Protein-coding gene on chromosome 19 (6,436,079 to 6,465,203, reverse strand). Ensembl gene ENSG00000125648.
Subcellular location: Mitochondrion inner membrane
Subcellular location (Human Protein Atlas): Mitochondria
Gene Ontology:
Molecular function: adenine nucleotide transmembrane transporter activity; ADP:phosphate antiporter activity; ATP:phosphate antiporter activity; protein binding; calcium ion binding
Biological process: adenine nucleotide transport; calcium import into the mitochondrion; mitochondrial ATP transmembrane transport; mitochondrial calcium ion transmembrane transport; positive regulation of mitochondrial calcium ion concentration; regulation of cellular hyperosmotic salinity response; ADP transport; transmembrane transport
Cellular component: mitochondrion; mitochondrial inner membrane
Genetic constraint (gnomAD): Loss-of-function variants: 33 observed, 53.61 expected, observed/expected ratio (o/e) 0.62, 90% interval 0.47 to 0.82. The upper end of that interval is the gene's LOEUF score, 0.82, which puts it in group 3 of 6, group 1 being the genes least tolerant of losing a copy. Missense variants: 574 observed, 631.51 expected, observed/expected ratio (o/e) 0.91, 90% interval 0.85 to 0.97. Synonymous variants: 275 observed, 257.92 expected, observed/expected ratio (o/e) 1.07, 90% interval 0.96 to 1.18.
Homologues: Orthologues: chimpanzee SLC25A23 (99% identical), macaque SLC25A23 (99% identical), dog SLC25A23 (95% identical), pig SLC25A23 (95% identical), rat Slc25a23 (94% identical), mouse Slc25a23 (94% identical), guinea pig SLC25A23 (91% identical), tropical clawed frog slc25a23 (72% identical), zebrafish slc25a23b (69% identical), zebrafish slc25a23a (69% identical). Paralogues in human: SLC25A25 (67% identical), SLC25A24 (60% identical), SLC25A41 (44% identical), SLC25A12 (23% identical), SLC25A13 (23% identical), SLC25A29 (18% identical), SLC25A38 (18% identical), SLC25A37 (17% identical), SLC25A42 (17% identical), SLC25A28 (17% identical), SLC25A16 (17% identical), SLC25A39 (16% identical), and 37 more.
Diseases named in the same sentence as SLC25A23 in open-access papers:
SLC25A23 is named in the same sentence as 20 diseases in open-access papers, as found by Europe PMC text mining. Sharing a sentence is not in itself a finding about the gene and the disease. The quoted sentences say what the papers report.
cervical squamous cell carcinoma (1 paper, 2022). A squamous cell carcinoma arising from the cervical epithelium. "Some genes of SLC25 were associated with poor prognosis of patients in cervical squamous cell carcinoma and endocervical adenocarcinoma, including SLC25A4, SLC25A5, SLC25A8, SLC25A14, SLC25A12, SLC25A23, and SLC25A41." (PMID 36254139, 2022).
colon cancer (1 paper, 2022). "The results showed that SLC25A4 and SLC25A23 were, respectively, decreased in gastric cancer and colon cancer, while SLC25A7 was increased in gastric cancer, which was consistent with our bioinformatics prediction." (PMID 36254139, 2022). "At the mRNA level of specimens, we found that SLC25A4 and SLC25A23 were, respectively, decreased in gastric cancer and colon cancer, while SLC25A7 was increased in gastric cancer, which was consistent with our bioinformatics prediction." (PMID 36254139, 2022). "In colon cancer, SLC25A7 expression was elevated while SLC25A23 was reduced." (PMID 36254139, 2022). "SLC25A4 was downregulated in gastric cancer specimens, while SLC25A23 was downregulated in colon cancer specimens without statistical significance." (PMID 36254139, 2022).
Crohn disease (1 paper, 2021). A gastrointestinal disorder characterized by chronic inflammation involving all layers of the intestinal wall, noncaseating granulomas affecting the intestinal wall and regional lymph nodes, and transmural fibrosis. "Some ICGs, such as BDH2, CYP4V2, OIT3, PLD1 and SLC25A23, were reported as differentially expressed in ileum tissue from Crohn’s disease vs. non-inflammatory bowel disease control." (PMID 34098982, 2021).
gastric cancer (1 paper, 2022). A primary or metastatic malignant neoplasm involving the stomach. "SLC25A23 mutation was significantly correlated with its expression in gastric cancer." (PMID 36254139, 2022). "To verify the positive results in result 3.8, we further detected the expression of SLC25A7 in gastric and intestinal cancer, SLC25A4 in gastric cancer, and SLC25A23 in intestinal cancer by immunohistochemistry." (PMID 36254139, 2022).
head and neck squamous cell carcinoma (1 paper, 2022). A squamous cell carcinoma that arises from any of the following anatomic sites: lip and oral cavity, nasal cavity, paranasal sinuses, pharynx, larynx, and salivary glands. "In head and neck squamous cell carcinoma, SLC25A9, SLC25A23, SLC25A4, and SLC25A5 all showed decreased expression." (PMID 36254139, 2022).
lung carcinoma (1 paper, 2022). "SLC25A23 was mainly expressed in lung cancer and ovarian cancer cells to some extent." (PMID 36254139, 2022).
major depressive disorder (1 paper, 2023). An episode of depression lasting two or more weeks without an intervening episode of mania. "Moreover, SLC25A23 was identified as a candidate biomarker gene that can improve low mood state of major depressive disorder (MDD); a recent study further confirmed this finding and demonstrated that up-regulation of SLC25A23 might be associated with MDD." (PMID 36970281, 2023).
ovarian carcinoma (1 paper, 2022). A malignant neoplasm originating from the surface ovarian epithelium. "Relatively high mutation rates were also observed in ovarian cancer cell lines for SLC25A13, SLC25A24, SLC25A41, and SLC25A23 and in skin cancer cell lines for SLC25A13, SLC25A8, and SLC25A12." (PMID 36254139, 2022).
uterine corpus endometrial carcinoma (1 paper, 2022). A endometrial carcinoma (disease) that involves the body of uterus. "Almost all SLC25s had high mutation frequency in uterine corpus endometrial carcinoma, including SLC25A12, SLC25A13, SLC25A14, SLC25A23, SLC25A24, and SLC25A25." (PMID 36254139, 2022).
cancer (1 paper, 2022). A tumor composed of atypical neoplastic, often pleomorphic cells that invade other tissues. "Therefore, SLC24A4, SLC25A7, and SLC25A23 were selected for subsequent validation of in situ expression in isolated fresh human cancer tissue by qPCR and IHC." (PMID 36254139, 2022). "The study would provide theoretical basis for their application as potential targets of cancer therapy including SLC25A4, SLC25A7, and SLC25A23." (PMID 36254139, 2022). "Several genes were selected for the validation of expression in fresh cancer tissue by qPCR and IHC including SLC25A4, SLC25A7, and SLC25A23." (PMID 36254139, 2022). "On the contrary, SLC25A23 and SLC25A13 had medium-to-low protein expression levels in some cancer." (PMID 36254139, 2022).
tumour (1 paper, 2010). "Scaled expression levels across the remaining nine candidate ECs analysed indicated within-gene differences in expression between tumour and normal tissue groups in both SLC25A23 (p = 0.040) and CHRNB4 (P = 0.002) but not in the remaining genes (p > 0.05)." (PMID 20122155, 2010).
SLC25A23 also shares sentences with these, for which no sentence is quoted: colon adenocarcinoma (1 paper); colorectal tumours (1); diffuse large B-cell lymphoma (1); endocervical adenocarcinoma (1); hemangioma (1); inflammatory bowel disease (1); intestinal cancer (1); metabolic syndrome (1); skin cancer (1).